CD4 (CD4 molecule)
Diseases named in the same sentence as CD4 in open-access papers (continued):
Sharing a sentence is not in itself a finding about the gene and the disease.
breast cancer (continued). "For ER+ breast cancer, the selection criteria revealed 8 cell types: iCAF, myCAF, cancer luminal A, macrophages, ACKR1+ endothelial cells, differentiated PVLs, CD4+ T cells, and CD8+ T cells (8×8=64 possible source/target cell combinations)." (PMID 39483921, 2024). "On the other hand, the levels of CD4+T cells, CD8+T cells, CD4+/CD8+ ratio, DNT cells, and NK cells in breast cancer patients have been reduced to different degrees within the lymphocyte subsets." (PMID 38263363, 2024). "It showed that CD3+T cells, CD4+T cells, CD8+T cells, CD4+/CD8+ ratio, DNT cells, NK cells, and LMR were significantly lower in the breast cancer group than in the group with benign breast lesions." (PMID 38263363, 2024). "In our study, we observed that CCT2 silencing in breast cancer cells led to enhanced activation (CD40L) and the proinflammatory cytokine (IFN-γ and TNFα) production in CD4+ T cells within the tumor microenvironment." (PMID 39079960, 2024). "In this study, we found that the levels of CD3+T, CD4+T and CD8+T cells were significantly reduced in the peripheral blood of breast cancer patients with high Ki-67 expression." (PMID 38263363, 2024). "In breast cancer, the expression of FOXP1 is positively correlated with the infiltration of CD4 + T cells, CD8 + T cells, neutrophils and macrophages, but different from our findings, the expression of FOXP1 is negatively correlated with B cells." (PMID 38652109, 2024). "We observed low expression of ESR-1 in CD4+ T, CD8+ T, and NK cells when compared with the ESR+ breast cancer cell line T47D." (PMID 39078714, 2024). "In addition, a recent study by Zhou suggested that microwave ablation may be not only a prominent local therapy for breast cancer, but also an inducer of antitumor immunity (Th1-type immune response and CD4 + TEM response)—exceedingly beneficial for the long-term prognosis of the patient." (PMID 38499835, 2024). "To further investigate the potential synergistic benefits of Chrysin@mPDA + PTT treatment for breast cancer, we conducted an analysis of the subpopulations of CD3+CD4+ helper and CD3+CD8+ cytotoxic T cells." (PMID 39045563, 2024). "TILs in breast cancer (BC) consist mainly of CD8+ cells, CD4+ cells, FOXP3+, and CD19+ cells, and less frequently CD56+ NK cells." (PMID 38672117, 2024). "In breast cancer, the high expression of SLAMF1, SLAMF7, CD48, and IGLL1 is positively correlated with the infiltration of B cells, CD8 + T cells, CD4 + T cells, macrophages, neutrophils, and dendritic cells." (PMID 38388382, 2024). "This study uses molecular imaging to evaluate changes in CD4 + T cells and CD8 + T cells during ICB in breast cancer models and examines biomarkers of response." (PMID 38918836, 2024). "In conclusion, this study has shown that compared to healthy women, breast cancer survivors exhibited higher levels of CD4+ central memory T cells, lower levels of CD8+ naïve T cells and higher activation levels of CD4+ and CD8+ effector-memory T cells." (PMID 37324393, 2023). "Our study has shown that ILC patients with low density of CD4, CD8, CD20, CD56, CD68, and FOXP3 had significantly longer DFS and OS, in contrary to TILs in TNBC and HER2‐positive breast cancer." (PMID 38151972, 2023). "PTPN1 expression showed a significant positive correlation with most types of immune cells, including B cells, CD4+ T cells, CD8+ T cells, neutrophils, macrophages, and dendritic cells in most cancer types, especially in breast cancer (P < 0.05 for all)." (PMID 37936713, 2023). "In breast cancer, ECM-related CAFs increase the protein expression of PD-1 and CTLA4 on the surface of CD4+CD25+ T lymphocytes and participate in immunotherapy resistance." (PMID 37199594, 2023). "In breast cancer patients with obesity, the immune system is dysregulated with an increase in pro-inflammatory adipokines, such as CD8+, Th1 CD4+, and Th17 CD4+, and a decrease in anti-inflammatory adipokines, such as Th2 CD4+ and Tregs." (PMID 37173991, 2023).
breast cancer (continued). "ER positivity was associated with decreased leukocyte density and reduced infiltration of total T, CD4+ T, Mo/Mφ, MDSC, DC, and mDC in breast cancer tissue." (PMID 36721218, 2023). "The soluble form of LAG-3 was detectable only in small amounts in the HTM, although elevated LAG-3 expression was found on the CD4 and CD8 T cells in the MDA-MB-231 HTM and PDX model as well as in the dataset of breast cancer patient samples." (PMID 37174080, 2023). "In a preclinical mouse model of HER2+ breast cancer, class II HER2 peptide pulsed DC1 (Class II HER2-DC1) drove CD4+ and CD8+ T cells infiltrating into tumors and delayed tumor growth." (PMID 37007133, 2023). "For instance, increased expression of ICOS was observed on CD4+ T cells from peripheral blood and tumor tissues of patients receiving anti-CTLA4 therapy in several types of cancer, including breast cancer, lung cancer, and bladder cancer." (PMID 38127899, 2023). "CD1C levels were positively correlated with CD8+T, CD4+T, and NK cells, explaining the protective roles of CD1C in breast cancer." (PMID 36755259, 2023). "In breast cancer, FAP+ CAFs particularly the ECM-myCAF and TGFβ-myCAF clusters, increase PD-1 and CTLA-4 expression on the surface of CD4+CD25+FOXP3+ Tregs." (PMID 37166418, 2023). "Silibinin has been shown to increase the number of CD4+ and CD8+ T cells and neutrophils but decrease macrophage and MDSCs cell numbers in 4T1 luciferase-transfected mammary cancer in female BALB/c and CB17-Prkdc Scid/J mice." (PMID 38139779, 2023). "Splenic CD4+ and CD8+ T cells were isolated using MACS and cocultured with 4T1 murine mammary cancer cells labeled with calcein-AM." (PMID 37108179, 2023). "Bioinformatic analysis showed that HK2 expression is associated with upregulated CD274 mRNA expression, reduced infiltration of CD4+ and CD8+ T cells in breast cancer specimens, and decreased survival time of breast cancer patients." (PMID 37377974, 2023). "We retrospectively included 112 patients with locoregional recurrent breast cancer, and hematoxylin–eosin staining and immunohistochemical staining (CD3, CD4, CD8, CD19, CD38, and CD68) were performed on locoregional recurrent tumor samples." (PMID 38133211, 2023). "In another neoadjuvant PAMELA phase II trial, 231 regions of interest (ROIs) from 129 HER2+ breast cancer patients were stained with six markers, including cytokeratin, Ki67, and four immune-related T-cell lineage markers (CD3, CD4, CD8, and Foxp3)." (PMID 37284197, 2023). "CXCL10 acts on CD4 + and CD8 + T cells to enhance antitumor immunity, and the serum level of CXCL10 in breast cancer patients is positively correlated with tumor size and ER status." (PMID 36797662, 2023). "On the other hand, γ-tocotrienol has been shown to raise circulating CD4+/CD8+ T-cells and natural killer cells, but to suppress regulatory T-cells in mice with mammary cancer." (PMID 37763286, 2023). "The signaling responsiveness of p-STAT5 to IL-7 stimulation was tested in CD4+ and CD8+ T cells; while all healthy donors (19/19) responded to IL-7, only 6/19 breast cancer patients responded to cytokine stimulation." (PMID 37741983, 2023). "The favorable effects of T cells including CD8 + T cells and some subtypes of CD4 + T cells such as TFH and Th1 in breast cancer have been revealed." (PMID 37828454, 2023). "Compared with that in patients with benign tumors, the proportion of CD4+Tn in patients with breast cancer patients decreased, whereas the proportion and absolute number of CD4+CD57+T and CD4+PD-1+T increased." (PMID 36925914, 2023). "In breast cancer, CD4 T cells can mitigate CD8 T cell exhaustion, and high infiltration levels of CD4 and CD8 T cells indicate favourable prognosis." (PMID 36993976, 2023). "Different subtypes of breast cancer can be identified using DSP technology; for example, regulatory T cell markers (CD4, CD25, and FOXP3) are highly expressed in basal-like and luminal breast cancers." (PMID 37744276, 2023).
breast cancer (continued). "In summary, the counts of CD4+ CM T cells were higher and CD8+ NA T cells lower among breast cancer survivors." (PMID 37324393, 2023). "For instance, NFKBIA mRNA levels positively correlated with the infiltration levels of M1 macrophages, CD4+ T cells, CD8+ T cells and naive B cells in breast cancer." (PMID 37775993, 2023). "Immunohistochemistry (IHC) analysis of immune cell populations (CD4, CD8 and CD68), cytokine (IL-2) and surface proteins (MHC class I and class II) were carried out to quantify their expression in mammary tumor tissues." (PMID 35972917, 2022). "CD4+ regulatory T (Treg) cells are a highly immunosuppressive subset that impedes immune surveillance of cancers, such as CRC, breast malignant tumors, and gastric cancer." (PMID 36275644, 2022). "Across all breast cancer subtypes, intratumoural CD8+ T cells are increased after NACT; meanwhile, the total CD3+ T cell compartment and the proportions of CD3+ CD4+ T cells and CD20+ B cells are reduced." (PMID 36139665, 2022). "In breast cancer (BRCA) tissues, the BACH1 expression was positively related to the infiltrating levels of CD8/CD4+ T cells, neutrophils, macrophages, and myeloid dendritic cells; but negatively related to that of B cells." (PMID 35651942, 2022). "In blood samples and invasive ductal carcinoma (IDC) tissue collected from breast cancer patients, Th17-related molecules (IL-17A, RORC, and CCR6), produced by tumor-infiltrating CD4+ and CD8+ T lymphocytes, were observed to be upregulated." (PMID 35954312, 2022). "In a breast cancer drug test, tremelimumab significantly increased the ratio of ICOS+/FoxP3+ CD4+ T cells in most patients and stablized the disease for more than 12 weeks in 42% of patients." (PMID 35799609, 2022). "Studies have demonstrated a correlation between improved clinical outcomes for breast cancer and greater CD8+ T and CD4+ T cell infiltration in tumors." (PMID 36353118, 2022). "Artemisinin remodeled breast cancer TME by increasing the numbers of tumorsuppressive CTLs and CD4+/IFN-γ+ Th1 cells, while concomitantly decreasing the numbers of tumorsupportive FOXP3+ Treg and T-bet+ MDSCs." (PMID 36700235, 2022). "Breast cancer TIME markers, including TILs, CD3, CD4, CD8, and PD-L1, were correlated with 21-gene RS score." (PMID 36528658, 2022). "In breast cancer, CD4 + and CD8 + expressed VISTA whereas in esophageal adenocarcinoma only CD4 + expressed VISTA; VISTA correlated with improved overall survival (OS)." (PMID 36058945, 2022). "In breast cancer patients, killer cell lectin-like receptor G1 (KLRG-1)+CD57+CD4+ and CD8+ senescent T cells that produce more effector cytokines, granzyme B and perforin accumulate in peripheral blood and in the tumor." (PMID 35326515, 2022). "SRC-3 inhibition by SI-2 and SRC-3 KD effectively increased the numbers of cytotoxic immune cells, such as CD4+ and CD8+ T cells and CD56+ NK cells, and Interferon γ (Ifng) in breast cancers compared to vehicle." (PMID 36316775, 2022). "Our findings provide novel insights into the mechanism of CD4+ T cell immunity and highlight TSLP induction as a potential therapeutic strategy in advanced breast cancer." (PMID 36467403, 2022). "In breast cancer, incubation of CD27+CD21lo/med B cells with CD4+ T cells promoted Th1 responses and suppressed Treg responses." (PMID 34374937, 2022). "Where the first CD4 results were less reproducible than CD8 results, a recent study on 272 breast cancer patients with over 10 years of follow-up showed that low CD4-RILA was associated with increased risk for both fibrosis and telangiectasia." (PMID 35565227, 2022). "In basal breast cancer, SDC1, CD4+ T cells, and DCs were negatively correlated with tumor survival; however, the associated molecular mechanism needs to be further verified." (PMID 35037689, 2022). "Increased numbers of both CD4+ CD25+ Tregs and myeloid-derived suppressor cells (MDSCs) were found in the peripheral blood of breast cancer patients." (PMID 35335881, 2022).
breast cancer (continued). "Following in vitro CD4+ T cell subset analysis, CD4+ T cells from blood, lymphocyte, and TIL samples from patients with untreated primary breast cancer were analyzed." (PMID 35158758, 2022). "We performed immunofluorescence staining of breast cancer tissues and found that CCL5 and CCR5 were mainly expressed in CD4+ T cells but rarely expressed in CD8+ T cells." (PMID 36033472, 2022). "In breast cancer, the expression levels of METTL14 have a positive correlation with the infiltration of CD4+ T cells, CD8+ T cells, dendritic cells, macrophages and neutrophils, but they negatively correlated with Treg cells in breast cancer." (PMID 36407103, 2022). "Another comparison between CD4, CD8 and NK-RILA in breast cancer patients showed that both CD8 and NK lymphocytes were associated with late toxicity." (PMID 35565227, 2022). "Collectively, our research on TSLP induction in breast cancer reveals that during the early stages of breast cancer development, cancer cells respond to TSLP-activated CD4+ T cell immunity by undergoing terminal differentiation." (PMID 36467403, 2022). "ICOS hi CD4+ T cells expressed IFN-y instead of IL-10, and were also capable of inducing lysis of human breast cancer cells expressing Mam-A protein." (PMID 35804943, 2022). "BRD4 gene expression was shown to have an immunomodulatory function in breast cancer and was positively correlated with the levels of infiltrating B cells, CD8 + T cells, CD4+ T cells, macrophages, neutrophils, and dendritic cells (DCs)." (PMID 36614001, 2022). "This study founded that the expression of RUNX2 was positively related to the immune infiltration of CD4+ T cells, CD8+ T cells, B cells, neutrophils, DC cells, and macrophages in the breast cancer microenvironment." (PMID 36092942, 2022). "Breast cancer TILs primarily contain CD8+ and CD4+ T cells, with smaller amounts of regulatory T cells (Treg), B cells, NK cells, and macrophages." (PMID 36551522, 2022). "Our study included Luminal breast cancer patients with 21-gene RS and TIME profiling and found that stromal TILs, CD3, CD4, CD8, and PD-L1 were generally positively correlated with each other." (PMID 36528658, 2022). "Other studies have reported altered CD4+ and CD8+ T-cell frequencies in blood and tumours of dogs with mammary neoplasms; however, these findings remain controversial." (PMID 35512031, 2022). "CD4+ and CD8+ T cells are the main types of lymphocytes in breast cancers and play a central role in the induction of efficient immune responses against tumors." (PMID 35454849, 2022). "In some NRF2-positive breast cancers, immune cells, such as CD8+ T, CD4+ T, dendritic, and stromal cells (such as adipocytes, fibroblasts, and keratinocytes), are highly infiltrated." (PMID 35707265, 2022). "Previous studies have found that in breast cancer, PDGFRB+CAFs recruit CD4+CD25+FOXP3+ Treg cells, and the recruited Treg cells inhibit the activation and proliferation of CD8+T cells in the TME, thereby inducing local immunosuppression." (PMID 35967414, 2022). "In vitro co-culture experiments using patient-derived CD4+ T cells primed with HER2 peptides and breast cancer cells with HER2 overexpression confirmed the observed effects." (PMID 35326515, 2022). "We found that T cell CD8+, T cell CD4+ memory resting, myeloid DC resting and monocyte infiltration were negatively correlated with LSM1 expression in the breast cancer infiltrate cohort." (PMID 35692083, 2022). "In breast cancer patients, a high amount of TGFβ released by tumor cells, combined with sustained TCR-stimulation, increases the acquired expression of FOXP3 in CD4+CD25- T cells, allowing them to develop into Treg cells." (PMID 35222362, 2022). "While most FDA-approved immunotherapies target CD8+ cytotoxic T cells, the role of CD4+ helper T cells and CD163+ macrophages is less well defined but increasingly seen as key players in the breast cancer microenvironment." (PMID 36376974, 2022).
breast cancer (continued). "More recently, treatment of a HER2+ breast cancer cell line tumor in a humanized mouse model with a trispecific antibody to HER2, CD3, and CD28 and adoptive transfer of CD4+ T cells demonstrated regression of cancer." (PMID 36159781, 2022). "In conclusion, stromal TILs, CD3, CD4, CD8 and tumor PD-L1 were generally positively correlated with each other in HR-positive/HER2-negative, breast cancer patients." (PMID 36528658, 2022). "In colon cancer, sarcoma, and breast cancer models, MHC class II-mediated tumor rejection is dependent on both CD4 and CD8 T cells." (PMID 35565329, 2022). "More than 70% of tumor stroma in breast cancer is infiltrated by different subpopulations of lymphocytes particularly CD8+ T cells and CD4+ T helper (Th) cells which can detect tumor antigens in immunocompetent hosts to initiate killing of cancer cells." (PMID 35972917, 2022). "The expression of CD4, KLRG-1, and CD57 correlates with increased overall survival for breast cancer patients." (PMID 35326515, 2022). "4T1 mouse mammary tumor model is suitable for assessment of metastasis due to its similarity to human breast cancer, particularly to determine immunotherapeutic response via infiltration of CD8+ and CD4+ T cells." (PMID 35972917, 2022). "Inflammatory cell infiltrates consisting of lymphocytes (CD4+ and CD8+ T cells and B+ cells) and macrophages are a common feature of breast cancer." (PMID 34359821, 2021). "Activated CD4 positive memory T cells, CD8 positive follicular helper T cells, and regulatory T cells are significantly dysregulated in breast cancer tissues." (PMID 34572478, 2021). "The percentage contents of CD4+ and CD8+ cells were also significantly increased in mammary tumors of MMTV-PyVT mice treated with adiponectin-expressing EGFP+ thymocytes." (PMID 33727658, 2021). "In the luminal breast cancer, ACE2 is related to the immune infiltration of CD8+ T cells (r = 0.184, p < 0.001), CD4+ T cells (r = 0.104, p = 0.02) and neutrophils (r = 0.101, p = 0.02)." (PMID 34413267, 2021). "On the contrary, we observed that application of anti-CTLA-4 (and PD-1 partially) antibodies into the tumor micro-environment inhibits CD4+ and CD8+ cell activity affecting their interaction with breast cancer cells." (PMID 34440813, 2021). "TGF-β suppresses CD4+ T helper 2 cell-mediated anti-cancer immunity, and blocks TGF-β signaling prevents breast cancer progression." (PMID 34762599, 2021). "While in luminal subtype of breast cancer, the ACE2 expression was strongly positively correlated with the immune infiltration level of CD8+ T cell (r=0.184, p<0.001), CD4+ T cell (r=0.104, p=0.02) and neutrophil (r=0.101, p=0.02)." (PMID 34413267, 2021). "TILs in breast cancer mainly comprise CD8 T cells, CD4 T cells, B cells, dendritic cells, and granulocytes." (PMID 34526986, 2021). "CD4+ CD25+ Tregs were well-known to reduce antitumor immunity, and Tregs increased side population of mouse breast cancer cells, promoted sphere formation, and upregulated stemness-related genes." (PMID 34745015, 2021). "In breast cancer, the HPSE expression showed a medium correlation with infiltrating levels of B cells, CD8+ T cells, CD4+ T cells, and macrophages, and a strong correlation with infiltrating levels of neutrophils and DCs." (PMID 34461608, 2021). "In this work, we investigate Treg repertoire formation in breast cancer patients using bulk and single-cell TCR sequencing combined with single-cell transcriptome sequencing of Treg and Tconv CD4+ TC from peripheral blood and breast tumors." (PMID 33602930, 2021). "The copy number change of the RUNX2 gene was only positively correlated with the infiltration of four types of immune cells in breast cancer: CD8+T cells, CD4+T cells, macrophages, and neutrophils." (PMID 34485309, 2021).